TGFB1 (transforming growth factor beta 1)
Diseases named in the same sentence as TGFB1 in open-access papers (continued):
Sharing a sentence is not in itself a finding about the gene and the disease.
gastric cancer (continued). "TGFB1 has been shown to play a role in the immune escape of gastric cancer, with the mechanism likely involving the suppression of CD8+ T cells and increases in regulatory T (Treg) cells." (PMID 38748299, 2024). "Transforming Growth Factor-β (TGF-β) significantly affects gastric cancer, with increased levels observed in patients, promoting lymph node metastasis, along with mutation in TGFB1 and TGFB2." (PMID 39768197, 2024). "Bioinformatics analysis with TCGA data revealed that TGFβ1 mRNA level in stomach cancer specimen was positively correlated with TNM stage (P = 0.004), but negatively associated with overall survival (P = 0.022)." (PMID 37056931, 2023). "In this study, the impact of silencing Rac1 and Prex1 on transforming growth factor-beta 1-induced epithelial–mesenchymal transition and apoptosis of human gastric cancer cells MGC-803 and MKN45 was investigated." (PMID 37434402, 2023). "The crosstalk between gastric cancer cells and TANs clearly suggests that, in addition to exerting on tumor cells by autocrine way, tumor cell-derived TGFβ1 can promote tumor EMT by educating neutrophils in gastric cancer TME." (PMID 37056931, 2023). "The results showed that in gastric cancer TGFβ1, TGFβ2 and TGFβ3 expressions were strongly correlated with most of the immune cell infiltration levels." (PMID 36119489, 2022). "Survival analysis of GSE184336 showed shorter survival times in patients with high TGFβ1 and TGFβ2 expression, and similar results were seen in several gastric cancer datasets set." (PMID 36119489, 2022). "To verify the promoting effect of TGFβ on EMT, we added TGFβ1, TGFβ2 and TGFβ3 active proteins to the culture medium, respectively, and cultured gastric cancer cells in TGFβ environment to detect the changes of cancer cell phenotype." (PMID 36119489, 2022). "Recent studies have demonstrated that TGFB1 plays a vital role in the progression of various tumors, including ovarian, colorectal, cervical, and gastric cancers." (PMID 35593122, 2022). "It is worth noting that due to the strong heterogeneity among gastric cancers, TGFβ1 was negatively correlated with the infiltration level of most immune cells in GSE62254." (PMID 36119489, 2022). "In contrast, the migration ability of gastric cancer cells was reduced and statistically significant after silencing of TGFβ1, TGFβ2 and TGFβ3 genes." (PMID 36119489, 2022). "Transwell assay examined the change of gastric cancer cell migration ability in TGFβ experimental group and control group (HSA), and the migration ability of gastric cancer cells was enhanced under TGFβ1, TGFβ2 and TGFβ3 active protein stimulation conditions." (PMID 36119489, 2022). "TGFβ1, TGFβ2 and TGFβ3 were significantly positively correlated with immune cell infiltration in multiple gastric cancer datasets." (PMID 36119489, 2022). "In view of the important role of TGFβ in EMT, we used small interfering RNA (siRNA) to reduce TGFβ1, TGFβ2 and TGFβ3 gene expression in gastric cancer cells." (PMID 36119489, 2022). "Firstly, immunohistochemical experiments were performed on paraffin sections of gastric cancer to observe the main distribution of TGFβ1, TGFβ2 and TGFβ3 proteins in gastric cancer tissues." (PMID 36119489, 2022). "Activation of transforming growth factor-beta 1 Signaling in fibroblasts increases the motility and invasiveness of gastric cancer cells." (PMID 35047016, 2021). "The expression of BGN, LOX, MMP-9, SERPINE1, and TGFB1 proteins was significantly higher in the samples of gastric cancer patients compared to the healthy people." (PMID 34054953, 2021). "It has been reported that tumor‐infiltrating monocytes/macrophages induced NK cell dysfunction via TGFβ1, thus impairing the expression of IFNα, TNFγ, and Ki‐67 in tumor progression in gastric cancer." (PMID 33591628, 2021).
gastric cancer (continued). "Rhomboid 5 homolog 2 (RHBDF2) induces gastric cancer cell invasiveness by regulating Transforming Growth Factor Beta 1 (TGFB1) signaling, a finding that corresponds with our results." (PMID 33796525, 2021). "And CSF1R of CD8 + Tcell, CCL2, VSIG4 of M2 Macrophage, NRP1 of Th1, TGFB1 of Treg cell presented strong correction with PCOLCE expression in gastric cancer (P < 0.001; Cor value ≥ 0.40)." (PMID 33392251, 2020). "CSF1R of CD8 + Tcell, CCL2, VSIG4 of TAM, NRP1, TGFB1 of Th1 cell presented significantly correlate with PCOLCE expression in gastric cancer (P < 0.001; Cor value ≥ 0.40)." (PMID 33392251, 2020). "TGFβ1, which promotes the invasion of cancer cells, decreases the expression of ZO-2 in scirrhous gastric cancer cells." (PMID 31450555, 2019). "Peng LS, Zhang JY, Teng YS, Zhao YL, Wang TT, Mao FY, Lv YP, Cheng P, Li WH, Chen N, Duan M, Chen W, Guo G, Zou QM, Zhuang Y. Tumor-Associated Monocytes/Macrophages Impair NK-Cell Function via TGFb1 in Human Gastric Cancer." (PMID 30400822, 2018). "The present study analyzes the in situ TGFβ1 expression in 23 cases of lymphocyte-rich gastric carcinomas (Ly-rich GCs) using immunohistochemistry and in situ hybridization." (PMID 29594353, 2018). "Among them, TGFB1 presents special interest due to its role in gastric cancer development, progression and invasiveness." (PMID 23029430, 2012). "This is the first report, to our knowledge, involving TGFB1 and VEGF polymorphisms and survival in gastric cancer patients mainly consisting of a Caucasian population; however, there were some limitations to the present study." (PMID 19566948, 2009). "The risk associated with genotypes and haplotypes of four TGFB1 SNPs and four VEGF SNPs were determined by multivariate logistic regression analysis in 171 patients with gastric cancer and 353 cancer-free controls frequency-matched by age, sex and ethnicity." (PMID 19835575, 2009). "Several studies have investigated the association between TGFB1 and VEGF SNPs and risk of cancers, including breast cancer, lung cancer, and gastric cancer, but the results were inconsistent." (PMID 19835575, 2009). "The effect of TGFβ1 on the prognosis of gastric adenocarcinoma is correlated with macrophage types, M2 subtype macrophages induced by different inducers play different roles in the intervention of gastric cancer cell lines." (PMID 39991579, 2025). "TGFβ1-induced M2c subtype macrophages have important interactions with gastric cancer cells (Hgc27 and MKN45) in terms of metastasis function and ferroptosis resistance and gastric cancer cells (Hgc27 and MKN45) provide important material basis for M2c macrophage polarization." (PMID 39991579, 2025). "The RT-qPCR validation of TGFβ1 mRNA expression in gastric cancer cell lines showed that gastric cancer cells (Hgc27 and MKN45) showed varying degrees of elevation after 6 h, 12 h and 24 h of M2c intervention, this change was positively correlated with the intervention time." (PMID 39991579, 2025). "However, TGFβ1 is also thought to play an oncogenic role in a few types of tumors, such as gastric cancer and melanoma." (PMID 38688896, 2024). "Furthermore, TGFβ1 mRNA level was positively correlated with FAM3C level in gastric cancer (P = 0.002)." (PMID 37056931, 2023). "However, the potential functions and mechanisms of TGFβ1, TGFβ2 and TGFβ3 in gastric cancer progression and tumor immunology are unclear." (PMID 36119489, 2022). "In this study, we analyzed the transcriptomic dataset GSE184336 of 231 gastric cancer patients, and the results showed that TGFβ1, TGFβ2 and TGFβ3 were highly expressed in cancer tissues, and western blot assays further confirmed the differences in TGFβ expression." (PMID 36119489, 2022).
gastric cancer (continued). "In this study, we comprehensively analyzed TGFβ1, TGFβ2 and TGFβ3 and gastric cancer microenvironmental features, including immune cell infiltration, EMT, hypoxia, mutation, immunotherapy and drug treatment, based on HMUCH sequencing data (GSE184336) and public databases." (PMID 36119489, 2022). "In addition, a previous study confirmed that the presence of an miR-335 mimic decreased the transcript expression levels of TGFB1, while the miR-335 inhibitor increased it in gastric cancer cell lines." (PMID 30717351, 2019). "Recent studies assigning a dominant gatekeeper role for TGFβ3 in malignant glioblastoma progression, as well as specifically implicating TGFβ1 in breast and gastric cancers, support the continued pre-clinical and clinical investigation of these novel TGFβ antibodies." (PMID 30400822, 2018). "In addition, EMT regulators, such as Snail and Slug, were upregulated in lysates and exosomes derived from DSGOST-treated gastric cancer cells, and TGFβ1 plus DSGOST treatment induced EMT signaling via phosphorylation of Smad2 and Smad3." (PMID 29844404, 2018). "For example, TGFβ1-induced LncRNA UCA1 upregulation promotes gastric cancer invasion and migration." (PMID 30250403, 2018). "Data from one multicenter transcriptome study and The Cancer Genome Atlas established the significance of transforming growth factor beta 1 (TGF)-β1 signaling on gastric cancer progression, supporting its role as an emerging candidate biomarker for gastric cancer." (PMID 26846663, 2016). "Our study suggested that TGFB1+915CG/CC and VEGF -634CG genotypes may be associated with short-term survival in gastric cancer patients." (PMID 19566948, 2009). "We hypothesized that potentially functional polymorphisms in TGFB1 and VEGF would be associated with clinical outcomes in patients with gastric cancer." (PMID 19566948, 2009). "In summary, we found that some polymorphisms TGFB1 and VEGF may be associated with 1- or 2-year survival rates of gastric cancer patients." (PMID 19566948, 2009). "In the present study, we did not observe a significant association between TGFB1 SNPs and gastric cancer risk, partly because our study size was small." (PMID 19835575, 2009). "Therefore, we speculate that M2c macrophages have an impact on gastric cancer cell lines by altering TGFβ1, further activating the TGFβ1/Smad pathway, promoting epithelial mesenchymal transition of gastric cancer cells." (PMID 39991579, 2025). "Therefore, we speculate that the enhanced migration and invasion ability of gastric cancer cells in the co culture group of M2c macrophages induced by TGFβ1 is related to the activation of the TGFβ1/Smad pathway." (PMID 39991579, 2025). "Finally, it can be mentioned that, with the help of continuous bioinformatics analyses, BGN, LOX, MMP-9, SERPINE1, and TGFB1 proteins enhance the progression of gastric cancer; they play a significant role in the organization and communication of cells in the extracellular matrix." (PMID 34054953, 2021). "In TGFB1, we observed that the T allele of rs1800469 (C˃T at the 5’UTR region) was associated with decreased EC susceptibility under dominant model, which was consistent with the result in gastric cancer among the same ethnic population (cases/controls = 675/704, aOR = 0.65, 95% CI = 0.52–0.82)." (PMID 27171242, 2016). "However, the present study is small, and various genetic and epigenetic events may also have led to an association between TGFB1 and VEGF polymorphisms and gastric cancer prognosis and survival." (PMID 19566948, 2009). "Contrastingly, some studies have shown that miR-361-3p can act as a tumor suppressor gene, such as in gastric cancer, where it targets TGFB1 or RABL6 to inhibit the progression and metastasis of gastric cancer." (PMID 38282047, 2024).
gastric cancer (continued). "For instance, transforming growth factor-beta 1 (TGF-β1) and bone morphogenetic protein 2 (BMP2) were detected in plasma exosomes from gastric cancer patients and gastric cancer cell-derived exosomes, respectively." (PMID 36967787, 2023). "The results of this study showed that TGFβ1, TGFβ2 and TGFβ3 were positively correlated with EMT, CDH2, VIM and ZEB1 and significantly negatively correlated with CDH1 in multiple gastric cancer datasets." (PMID 36119489, 2022). "In gastric cancer dataset STAD, GSE63089 and dataset GSE184336, the expression levels of TGFβ1, TGFβ2 and TGFβ3 were higher in cancer tissues than in normal tissues adjacent to the cancer." (PMID 36119489, 2022). "We demonstrated that miR-10b-5p targets PTEN of gastric cancer cells and KLF11 of fibroblasts and mediates the communication of gastric cancer cells and fibroblasts via TGFβ1/TGFβR1 signaling." (PMID 33754012, 2021). "The expression levels of TGFB1, TGFB2, ZEB1 and PTBP1 were detected by qRT-PCR in 92 pairs of gastric carcinoma specimens and adjacent normal tissues (Cohort 2)." (PMID 34706749, 2021). "We found that DCLK1 expression significantly correlates with both TGFB1 and CXCL12 and their receptors TGFBR1, TGFBR2, and TGFBR3, and CXCR4, respectively, in colon and stomach cancer patients." (PMID 31979136, 2020). "We genotyped TGFB1 -509 C>T, +1869 T>C, and +915 G>C and VEGF -1498T>C, -634G>C, and +936C>T in 167 patients with gastric cancer." (PMID 19566948, 2009). "In this study, the potential target of HL-RG in the treatment of gastric cancer was studied Through PPI network analysis and molecular pairing, TGFB1, CCND1, MMP9, ERBB2, CAT, and PPARα may be the core targets of HL-RG in the treatment of RCC." (PMID 41305721, 2025). "However, in the M2 subtype detection, our research results only support that the metabolites of gastric cancer cells (Hgc27 and MKN45) have a similar effect on M2 subtype macrophages to TGFβ1." (PMID 39991579, 2025). "The scratch test results showed that the subtypes of macrophages formed by TGFβ1 intervention group were co cultured with gastric cancer cells (Hgc27 and MKN45) for 12 and 24 hours, and the proliferation ability of gastric cancer cells (Hgc27 and MKN45) was significantly enhanced." (PMID 39991579, 2025). "Thus, after silencing the TGFβ gene in gastric cancer cells, the progression of EMT was significantly inhibited, and all of these results together suggest that TGFβ1, TGFβ2 and TGFβ3 are key factors in regulating the progression of EMT." (PMID 36119489, 2022). "Consistently, previous studies reported that regulatory T-cells (Tregs) promote LGR5 upregulation in gastric cancer cells through TGFβ1 signaling, with a likely involvement of Wnt signaling; Meanwhile, high LGR5 levels upregulated by TGFβ1 was thought to deteriorate gastric cancer patient prognosis." (PMID 33767593, 2021). "Recently, fucoidan has been shown to inhibit transforming growth factor beta 1 (TGF-β1) secretion and affect cancer cell viability through increased expression of C-type lectin-like receptor 2 (CLEC-2) in several gastric carcinoma cells, demonstrating its anti-cancer potential." (PMID 34436275, 2021). "Because previous papers on the tissue distribution of TGFβ did not deal with immune responses in gastric cancer tissue, the present paper describes detailed TGFβ1 localization in immune cells in human cancer tissues for the first time." (PMID 29594353, 2018). "More interestingly, TGFβ1 could modulate EMT by impacting expression of lncRNAs and miRNAs in gastric cancer and bladder cancer." (PMID 30250403, 2018). "In contrast, neither TGFβ1 nor Ki26894 affected migration by the non-scirrhous gastric cancer cell lines used." (PMID 20145621, 2010). "Zuo uncovered that the elevation of UCA1 is correlated with the LNM of gastric cancer (GC); besides, UCA1 regulates the EMT of GC cells possibly through transforming growth factor-β1 (TGFβ1) induction in vitro." (PMID 29368602, 2018).
gastric cancer (continued). "However, the frequency distributions of these haplotypes between the cases and controls was not significantly different for both TGFB1 (P = 0.759) and VEGF (P = 0.808), nor were they associated with risk of gastric cancer." (PMID 19835575, 2009). "However, none of other TGFB1 and VEGF SNPs was associated with risk of gastric cancer." (PMID 19835575, 2009). "After adding RSL3 to the M2c macrophage co culture group induced by TGFβ1 77, there was no significant decrease in SOD and GSH levels, nor a significant increase in MDA levels in gastric cancer cells." (PMID 39991579, 2025). "In our cluster analysis of the TCGA data of gastric cancer patients with N2 and N3 metastasis, the cases with high ERBB2 expression formed clusters with cases that showed high SMAD2 expression, but not with the cases with a high expression of TGFB1, which is an upstream cytokine of SMAD2 signaling." (PMID 35650563, 2022).